CYSLTR2 (cysteinyl leukotriene receptor 2)
Diseases named in the same sentence as CYSLTR2 in open-access papers (continued):
Sharing a sentence is not in itself a finding about the gene and the disease.
ischemia (4 papers, 2017 to 2024). A hypoperfusion of the BLOOD through an organ or tissue caused by a PATHOLOGIC CONSTRICTION or obstruction of its BLOOD VESSELS, or an absence of BLOOD CIRCULATION. "Interaction of LTs with CYSLTR2 increases vascular permeability and amplifies the extent of the myocardial injury, and high levels of CYSLTR2 expression in the heart and vessels have been linked to a detrimental outcome in murine ischemia/reperfusion models." (PMID 30360467, 2018). "Inhibition of CysLTR1 or CysLTR2 protects against LPS or ischemia-induced microglial inflammation and brain injury." (PMID 37361996, 2023). "Accordingly, endothelial cysteinyl leukotriene 2 receptor (CYSLTR2) expression within the heart and vasculature is induced by ischemia/reperfusion injury." (PMID 30360467, 2018). "In vitro, CysLTR-1 mediates astrocyte proliferation after mild ischemia, whereas CysLTR-2 mediates astrocyte death after more severe ischemia." (PMID 28607533, 2017). "Neuroprotection is provided by the CysLTR1 antagonist Montelukast and the CysLTR2 antagonist HAMI3379, as they inhibit ischemia-induced microglial activation and pro-inflammatory cytokine release." (PMID 37361996, 2023).
atopic asthma (3 papers, 2013 to 2019). An asthma that is characterized by symptoms that are triggered by an allergic reaction caused by inhaled allergens such as dust mite allergen, pet dander, pollen and mold. "The 601 A > G variant of the CYSLTR2 gene, encoding the Met201Val CYSLTR2 receptor variant, is associated with atopic asthma in the general European population, where it is present at a frequency of ∼2.6%." (PMID 27990118, 2016). "Although the CYSLTR2 gene has been mapped to chromosome 13q14, a region linked to atopic asthma, it remains unclear how the gene is regulated." (PMID 23829413, 2013). "The presence of SNPs in both the CYSLTR1 and CYSLTR2 genes may increase the risk for atopic asthma." (PMID 27990118, 2016).
Cerebral ischemia (3 papers, 2017 to 2023). Restriction of arterial blood supply to the brain associated with insufficient oxygenation to support the metabolic requirements of the tissue. "Indeed, CysLTR-1 was involved in glial scar formation during the chronic phase after focal cerebral ischemia, and CysLTR-1 antagonist, but not CysLTR-2, was able to reduce the astrocyte response in the subacute phase after brain ischemia." (PMID 28607533, 2017).
atopic dermatitis (2 papers, 2022 to 2025). "Leukotrienes lead to acute pruritus in atopic dermatitis (AD) through CysLTR2 (Cysteinyl Leukotriene Receptor 2) receptors on a subset of NP3 sensory neurons." (PMID 35646918, 2022).
breast tumor (2 papers, 2016 to 2019). "The authors showed that both leukotriene receptor Leukotriene B4 receptor 2 (BLT2) and Cysteinyl leukotriene receptor 2 (CysLT2) were expressed in human breast tumor and matched lymph node metastases." (PMID 31616408, 2019).
cutaneous melanoma (2 papers, 2019 to 2021). A primary melanoma arising from atypical melanocytes in the skin. "Again, our findings regarding CYSLTR2 p.L129Q show similarities to BRAF p.V600E in cutaneous melanoma." (PMID 33588787, 2021).
lung carcinoma (2 papers, 2017 to 2025). "In addition, we presume that the mutated CYSLTR2 may be involved in lung cancer development through the production of aberrant GPCRs, based on the evidence observed in other cancers." (PMID 40768543, 2025).
adenoma (1 paper, 2023). A neoplasm arising from the epithelium. "CYSLTR1 and CYSLTR2 expression were significantly higher and lower in the primary tumor samples than in the adenoma and normal samples, but it was higher and lower in the metastatic specimens than in the primary tumor samples, respectively." (PMID 36834820, 2023).
aortic valve disease (1 paper, 2024). "Additionally, AS from LVH demonstrates upregulated anti-inflammatory COX receptor-related genes PTGER2 and PTGER4, and LOX-derived LT receptor-related gene CYSLTR2, but downregulated TBXAS1 and ALOX5, suggesting different mechanisms causing aortic valve disease and aortic calcification." (PMID 39062733, 2024).
autism (1 paper, 2024). Persistent deficits in social interaction and communication and interaction as well as a markedly restricted repertoire of activity and interest as well as repetitive patterns of behavior. "Six genes were significantly differentially expressed between autism likelihood (social communication) groups: CYSLTR2, NOX1, C1QA, CXCL10, C8A, IL23R (all up-regulated, p < 0.05)." (PMID 39247132, 2024). "There are no studies reporting an association between CYSLTR2 and autism." (PMID 39247132, 2024).
cerebral edema (1 paper, 2025). "LTC4 has also been implicated in promoting blood-brain barrier (BBB) disruption and inducing cerebral edema, and the use of CysLTR2 inhibitor HAMI3379 or specific knockdown of CysLTR2 expression significantly reduces post-ischemic reperfusion induced brain necrosis." (PMID 40390112, 2025).
esophageal cancer (1 paper, 2016). A primary or metastatic malignant neoplasm involving the esophagus. "Up-regulation of LTB4R and down-regulation of CYSLTR2 gene expression may occur already in normal squamous esophageal epithelium of patients with esophageal cancer suggesting a potential role of these receptors in early steps of esophageal carcinogenesis." (PMID 27475906, 2016).
esophageal squamous cell carcinoma (1 paper, 2016). Esophageal squamous cell carcinoma (ESCC) is a type of esophageal carcinoma (EC) that can affect any part of the esophagus, but is usually located in the upper or middle third. "Expression of LTB4R, LTB4R2, CYSLTR1 and CYSLTR2 was analyzed by immunohistochemistry (IHC) and quantitative reverse transcription-polymerase chain reaction (qRT-PCR) in biopsy samples of 19 patients with esophageal squamous cell cancer and 9 sex- and age-matched patients with functional dyspepsia." (PMID 27475906, 2016). "We aimed to investigate the expression of LTB4R, LTB4R2, CYSLTR1 and CYSLTR2 in esophageal squamous cell carcinoma and adjacent non-transformed squamous epithelium of the esophagus, as well as in control biopsy samples from esophageal squamous epithelium of patients with functional dyspepsia." (PMID 27475906, 2016).
gastric cancer (1 paper, 2017). A primary or metastatic malignant neoplasm involving the stomach. "Furthermore, results from Protein Atlas database validate immune molecules including CD86, CD209, C3AR1, CLEC4D, CLEC7A and CYSLTR2 are positive in gastric cancer cells." (PMID 29152078, 2017). "Overlap analysis with genes that co-expressing in 381 gastric cancer tissues and 37 gastric cells demonstrates that various immune related genes such as CCL18, TLR8, C3AR1, CYSLTR2 and CD86 are positively correlated with CD163." (PMID 29152078, 2017).
itch (1 paper, 2025). "N-met LTC4 can bind to Cysltr2 and activate Nppb+ DRG neurons to induce itch." (PMID 41451134, 2025).
Lewis lung carcinoma (1 paper, 2021). "A study using male C57BL/6 mice, including wild type, Cysltr1−/− and Cysltr2−/−, implanted with Matrigel plugs or subcutaneously injected with Lewis lung carcinoma cells demonstrated the important role of CysLT2R in regulating tumor angiogenesis, metastasis and endothelial cell dysregulation." (PMID 35008546, 2021).
liver cancer (1 paper, 2022). An epithelial or non-epithelial malignant neoplasm that arises from the liver. "We consider that it is enough for CysLTs/CysLTR2 signaling transduction to take a local or transient effect on inhibiting CYLD expression in liver cancer pathology." (PMID 35978827, 2022).
multiple myeloma (1 paper, 2022). "Previous studies have shown that the increase in B cells in malignant tumors may be associated with differential miRNA expression, and CYSLTR2 showed a positive association with miR-125b in multiple myeloma (MM) and causing abnormal infiltration of B cells in tumors." (PMID 35401882, 2022).
nevus (1 paper, 2021). Nevus (or naevus, plural nevi or naevi, from nævus, Latin for "birthmark") is the medical term for sharply circumscribed[1] and chronic lesions of the skin or mucosa. "In nevus 12B, the only one being GNAQ and GNA11 wild-type, we now identified this CYSLTR2 mutation, while only CYSLTR2 wild-type alleles were detected in other nevi." (PMID 33588787, 2021).
rectal cancer (1 paper, 2023). A primary or metastatic malignant neoplasm that affects the rectum. "We observed a significant number of mutations in the CYSLTR1 and CYSLTR2 genes in CC, whereas the CYSLTR1 gene was not mutated in rectal cancer patients." (PMID 36834820, 2023).
rectal tumors (1 paper, 2023). "However, a significant decrease in positive M-values for the CpG probe cg16886259 and an increase in positive M-values for the CpG probe cg16299590 for CYSLTR2 were observed in the colon and rectal tumors compared with matched normal samples." (PMID 36834820, 2023).
tumor (38 papers, 2011 to 2025). "The identification of early mutations in genes such as GNAQ/11, BAP1 and CYSLTR2, among others, and the understanding of their roles in tumor growth and metastasis, have greatly enhanced our understanding of UM and provided potential targets for therapy." (PMID 38920653, 2024). "A recurrent, hotspot mutation, p.Leu129Gln in CYSLTR2, an oncogene driver in uveal melanoma and leptomeningeal melanocytic tumors, leads to the activation of endogenous Gαq signaling and contributes to tumor progression in vivo." (PMID 36834820, 2023). "The comparable abundances (~ 74% of total tumour) of the CYSLTR2 mutation, gain of 8q and losses of 1p and 16q suggest that these alterations are clonally present in this sample and occurred during an early developmental phase." (PMID 33588787, 2021). "Whereas the CYSLTR2 p.L129Q mutation is likely to be the initiating oncogenic event, various mechanisms further increase the mutant allele abundance during tumour progression." (PMID 33588787, 2021). "According to functional studies, CYSLTR1 mediates preferentially pro-carcinogenic effects, whereas CYSLTR2 has been associated with anti-tumor mechanisms." (PMID 27475906, 2016). "Paired baseline and on-treatment samples (time from baseline to on-treatment sample 0.9–11.3 months) from 17 patients were sequenced and the driver GNAQ, GNA11 and CYSLTR2 mutations identified in the tumor were confirmed by NGS in the baseline and/or on-treatment ctDNA samples in 16/17 patients." (PMID 33917514, 2021). "In our cohort we identified one tumor with CYSLTR2 mutation." (PMID 31173078, 2019). "On the other hand, CDH1 and VIM expression were higher in tumor samples with high expression of the CYSLTR2 gene." (PMID 36834820, 2023). "The M values of cg16299590 and cg16886259 CpG probes for the CYSLTR2 gene were significantly high in tumor samples than in normal areas." (PMID 36834820, 2023). "The M values of the CpG probes for CYSLTR1 are significantly lower in primary tumor and metastasis samples than in matched normal samples, but those for CYSLTR2 are significantly higher." (PMID 36834820, 2023). "CYSLTR1 and CYSLTR2 expression were significantly differentially regulated between CRC tumor tissues and corresponding normal tissues in the TCGA-COADREAD cohort." (PMID 36834820, 2023). "Based on the expression level of the CYSLTR2, tumor samples were divided into high-expression and low-expression groups." (PMID 35401882, 2022). "Given that a variety of immune cells is known to express CYSLTR2, we investigated the cellular origin of this expression in these tumours." (PMID 33588787, 2021). "Whereas most tumours harbour a mutation in GNAQ or GNA11, CYSLTR2 (encoding G-protein coupled receptor CysLT2R) forms a rare alternative." (PMID 33588787, 2021). "PUM-2 presented as a relatively stable tumour, but with a chromosome 13q alteration (leading to gain of mutant CYSLTR2) which also existed in a tumour subclone." (PMID 33588787, 2021). "Whereas most tumours harbour a hotspot mutation in GNAQ or GNA11, the CYSLTR2 p.L129Q mutation forms a rare alternative." (PMID 33588787, 2021). "In tumour V4-A9E8 a chromosome 13q copy number gain led to an allelic imbalance involving the CYSLTR2 locus, which was proportionately expressed at the RNA level." (PMID 33588787, 2021). "In two patients the tumor harbored a PLCB4 p.Asp630Phe mutation, in one patient there as a CYSLTR2 p.Leu129Gln mutations, and one patient was wildtype for these two genes as well." (PMID 34771480, 2021). "All but one tumour have a known UM driver gene mutation (GNAQ, GNA11, BAP1, PLCB4, CYSLTR2, SF3B1, EIF1AX)." (PMID 32415113, 2020). "Most UMs harbor one Gq pathway mutation (GNAQ, GNA11, CYSLTR2, or PLCB4), one BSE mutation (BAP1, SF3B1, or EIF1AX), and a few recurrent CNAs, in 100% of tumor cells." (PMID 29317634, 2018). "Hence, CYSLTR1 and CYSLTR2 expression influenced tumor metastasis through the alteration of EMT marker expression (CDH1 and VIM)." (PMID 36834820, 2023).
tumor (continued). "Likewise, CYSLTR2 expression was significantly decreased in CRC tumor tissues compared with corresponding normal tissues (p ≤ 0.00001, paired t-test)." (PMID 36834820, 2023). "Analysis of tumour biopsies (n = 63) showed that 61 (97%) had likely loss of one copy of BAP1, 23 (37%) had mutations in the gene encoding GNAQ, 26 (41%) in GNA11, three (5%) in CYSLTR2, one (2%) in PLCB4 and 11 (17%) in SF3B1." (PMID 36229663, 2022). "Based on bulk RNA data from the TCGA cohort, the highest levels of wild-type CYSLTR2 expression were observed in tumours with an inflammatory phenotype as shown by their immune gene expression signature (high expression of CD14, CD163 [monocytes/macrophages] and CD3D, CD8A [T cells])." (PMID 33588787, 2021). "Although in one case (PUM-1) this may be attributed to the elimination of the wild-type allele during tumour progression, in the other case (PUM-2), a wild-type copy of CYSLTR2 was still available." (PMID 33588787, 2021). "Assessment of known UM driver genes revealed an oncogenic driver mutation in 102 of 103 tumours: 51 in GNAQ (48 p.Q209P/L, two p.R183Q, one p.G48L), 46 in GNA11 (44 p.Q209L/P, two p.R183C), five in PLCB4 (three p.D630Y, two p.D630N) and two in CYSLTR2 (p.L129Q)." (PMID 32415113, 2020). "The losses of both wild-type CYSLTR2 and chromosome 3p were present in a significantly smaller, subclonal proportion of the cancer cells (67% of total tumour), which indicates that these alterations occurred later during tumour development and that these cells coexisted with the predecessor clone." (PMID 33588787, 2021). "The tumor with CYSLTR2 mutation showed detectable pMEK1/2 but no pERK1/2." (PMID 31173078, 2019). "Primary tumor tissues showed significant CYSLTR1 upregulation compared with matched normal tissues, whereas it was the opposite for the CYSLTR2." (PMID 36834820, 2023). "The CYSLTR1 and CYSLTR2 gene expressions gradually increased and decreased in stage II, III and IV primary tumor samples, respectively." (PMID 36834820, 2023). "In tumor samples, CYSLTR1 was significantly upregulated, but the opposite was true for CYSLTR2 expression." (PMID 36834820, 2023). "In the HPA database, protein expressions of the seven genes (ADAMTS8, CCR2, CYSLTR2, FAM129C, FCER1A, GAPT, PKHD1L1, and ZNF831) were markedly low in tumor tissues with less intense antibody staining and fewer stained cells in LUAD." (PMID 36033829, 2022). "In a clinical setting where tumor tissue is unavailable, comprehensive screening for all oncogenic mutations in both paralog genes GNAQ and GNA11 as well as in CYSLTR2 and PLCB4, would be necessary to improve the detection rate of tumor-derived DNA in ocular fluids." (PMID 40461505, 2025). "The CYSLTR1 and CYSLTR2 gene expressions and methylation were validated in an additional in silico cohort (E-MTAB), with the transcriptome and genome-wide methylation sequencing for primary tumor and normal samples." (PMID 36834820, 2023). "CysLTR2 expression in stromal cells, rather than tumor cells, is essential for enhanced invasiveness." (PMID 35978827, 2022).
cancer (17 papers, 2011 to 2025). A tumor composed of atypical neoplastic, often pleomorphic cells that invade other tissues. "In COAD, dysregulation of CYSLTR2 has been associated with the proliferation and migration of the cancer cells." (PMID 35401882, 2022). "Thus, there were few co-occurring mutations within the CYSLTR2 mutant cancers (between 5 and 19 coding mutations per sample), intuitively reducing the chance that the enrichment of semaphorin/plexin mutations in CYSLTR2 mutant UM relative to GNAQ/GNA11 mutant UM was a false discovery." (PMID 39013872, 2024). "Protein expression of LTB4R2 and CYSLTR2 was found to be significantly increased in cancer tissue compared to normal mucosa of cancer group and control (p < 0.05)." (PMID 27475906, 2016). "The expression of CYSLTR2 mRNA was reduced in cancer tissue to 0.23-fold and in normal epithelium of cancer patients to 0.25-fold compared to control." (PMID 27475906, 2016). "Notably, murine studies have shown that montelukast may also modulate the expression of cysteinyl leukotriene receptor 2 (CysLT2-R), suggesting potential therapeutic relevance in CYSLTR2-mutant cancers." (PMID 41353847, 2025). "The observed discordance between CYSLTR1, CYSLTR2 protein expression and gene transcription can be explained by the presence of leukotriene receptor positive inflammatory cells infiltrating transformed and non-transformed tissue of cancer patients." (PMID 27475906, 2016). "Similarly, non-transformed esophageal mucosa of cancer patients showed a significant reduction in CYSLTR2 mRNA transcription compared to the esophageal mucosa of dyspeptic control patients." (PMID 27475906, 2016).
cardiovascular diseases (3 papers, 2020 to 2025). "While CysLTR2 is generally considered to have a more prominent role in the cardiovascular system due to its high expression in the heart, it is increasingly recognized that both CysLTR1 and CysLTR2 play important but distinct roles in cardiovascular diseases." (PMID 41488008, 2025).
CNS neoplasms (2 papers, 2022 to 2024). "Additionally, molecular analysis of PLCB4 and CYSLTR2 and methylation profiling are especially useful in discriminating these lesions from other pigmented CNS tumors." (PMID 36497333, 2022).
CYSLTR2 also shares sentences with these, for which no sentence is quoted: metastatic disease (3 papers); atherosclerosis (2); chronic rhinosinusitis (2); inflammation (2); ischemic stroke (2); lung fibrosis (2); myocardial ischemia (2); nasal polyps (2); respiratory disease (2); allergic rhinitis (1); calcification (1); cancer of the eye (1); central nervous system disorder (1); chronic asthma (1); ciliopathies (1); colitis (1); colon polyps (1); colorectal adenocarcinoma (1); COVID-19 (1); Depression (1); functional dyspepsia (1); heart failure (1); injury (1); ischemia reperfusion injury (1); lymphoma (1); metastatic melanoma (1); myocardial infarction (1); Parkinson disease (1); Stroke (1).